AR (androgen receptor)
Diseases named in the same sentence as AR in open-access papers (continued):
Sharing a sentence is not in itself a finding about the gene and the disease.
prostate carcinoma (continued). "By unraveling the complex interplay between SPOP mutations and the AR signaling pathway, we aim to contribute to the ongoing efforts to improve our understanding of prostate cancer biology and enhance patient outcomes through more precise and effective therapeutic interventions." (PMID 40432836, 2025). "Importantly, HSP90, HSP72, and HSP27 have all been implicated in fueling AR signaling in prostate cancer." (PMID 39787247, 2025). "Biologically, androgen-driven prostate epithelial cell proliferation underlies prostate cancer’s exclusive male occurrence, while testosterone may promote bladder cancer progression via androgen receptor-mediated signaling." (PMID 40786297, 2025). "From the perspective of signaling pathways, mainstream research indicates that glutamine addiction is associated with the progression and metastasis of prostate cancer cells through three distinct pathways: the AR pathway, the MYC pathway, and the PTEN/PI3K/mTOR pathway." (PMID 41179661, 2025). "Variations in CAG repeat length relate to AR activity; shorter repeats may be associated with an increased risk of prostate cancer." (PMID 40008000, 2025). "Given the established role of lineage plasticity in the progression of prostate cancer and the loss of AR signaling pathway during NEPC development, we hypothesized that PROX1 plays a key role even prior to NEPC differentiation change." (PMID 40454483, 2025). "Furthermore, previous researches reveal that redistribution of key prostate cancer–associated TFs, AR and FOXA1, from epithelial‐associated to NE‐associated regulatory elements promote NE cell‐like lineage plasticity." (PMID 41415713, 2025). "Notably, this germline-driven convergence onto FOXA1/AR pathways parallels the well-established somatic mutations that also funnel into AR-regulated networks, underscoring a shared molecular axis of prostate cancer pathogenesis." (PMID 41468516, 2025). "Moreover, c-Myc plays a positive role in regulating androgen receptor and its splice variants in prostate cancer." (PMID 40044981, 2025). "Additionally, prolonged exposure to ADT or ARPis can induce AR mutations and gene amplification, thus promoting disease progression by increasing AR signaling and selecting for prostate cancer cells resistant to further treatment with these agents." (PMID 40627156, 2025). "This truncated fumaramide handle maintainedrobust degradation of BRD4 and expanded the scope of neo-substratetargets, including CDK4/6, SMARCA2/4, and notably, the androgen receptor(AR) and its therapeutically challenging truncation variant AR-V7in androgen-independent prostate cancer cells." (PMID 40726802, 2025). "Recent studies have shown that estrogen promotes endoplasmic reticulum-associated degradation and enhances the expression of the proto-oncogene c-Myc in prostate cancer cells through AR/ER signaling, highlighting the complex mechanisms underlying sex hormone action." (PMID 40303343, 2025). "Apart from AR mutations, other genetic alterations are also observed in prostate cancer." (PMID 40356745, 2025). "Identified as a risk factor, AR exerts a deleterious influence in prostate cancer." (PMID 40729027, 2025). "Moreover, extensive studies, including our previous work, demonstrated that somatic mutations in prostate cancer frequently converge on the FOXA1/AR pathways." (PMID 41468516, 2025). "Interestingly, PELP1 has been implicated in prostate cancer due to its role in enhancing AR transcription." (PMID 40023399, 2025). "Another study in a patient-derived xenograft model of castration-resistant prostate cancer also demonstrated that high BIRC6 protein levels were associated with resistance to the androgen receptor inhibitor enzalutamide and that targeting BIRC6 inhibited cancer growth both in vitro and in vivo." (PMID 40768895, 2025).
prostate carcinoma (continued). "In addition, prostate cancer cells develop mechanisms to survive in low-testosterone environments by increasing AR expression, acquiring AR gene amplifications, or producing AR splice variants that function independently of androgens." (PMID 41235005, 2025). "First, for prostate cancer patients at high risk of COVID-19 exposure or complications, regimens incorporating direct AR antagonists might offer dual benefits of oncologic control and potential viral protection." (PMID 41150771, 2025). "We demonstrate that pharmacological activation of ABHD5 with the synthetic ligand SR-3420 robustly suppresses c-MYC protein levels in two castration-resistant prostate cancer models expressing either wild-type or constitutively active, alternatively spliced androgen receptor variants." (PMID 41349769, 2025). "AR activity in prostate cancer is also intimately linked to BRD4." (PMID 40163908, 2025). "In addition, for PTEN-deficient prostate cancers, small-molecule inhibitors of Akt combined with second-generation AR pathway inhibition have demonstrated efficacy in mCRPC." (PMID 39919177, 2025). "Additionally, ARCC‐4 degraded significant clinical androgen receptor point mutations and had inhibitory effects on the proliferation of prostate carcinoma cells." (PMID 39898116, 2025). "AR signaling has been implicated in tumor growth and survival, making it a promising target for intervention Agents such as enzalutamide and bicalutamide, originally developed for prostate cancer, have demonstrated activity in AR-positive BCs." (PMID 41373752, 2025). "Furthermore, KDM4A was implicated in the regulation of androgen receptor (AR) expression in prostate cancer cells by the epigenetic modulation of AR enhancer." (PMID 40940894, 2025). "Furthermore, the authors elucidated that acquired resistance mechanisms to antiandrogen therapy in prostate cancer involved the AR, including AR mutations, amplifications, and rearrangements." (PMID 41020040, 2025). "Next, we expanded our studies to determine whether there is differential sensitivity to combined Akt and AR inhibition across a broad panel of endogenous PTEN-deficient prostate cancer organoids and cell lines." (PMID 39919177, 2025). "The CWR22Rv1 (22Rv1) cell line, another human prostate cancer cell line derived from xenografts of human metastatic prostate tumors, exhibits an intermediate profile with a mutated (overactive) AR and PSA expression, making it a unique tool for studying partial androgen signaling." (PMID 40709190, 2025). "Notably, the TMPRSS2-ERG fusion, which is present in approximately 50% of prostate cancers, leads to an AR-mediated upregulation of ERG signaling and is implicated in pathways that lead to metastasis rather than cell growth." (PMID 40075623, 2025). "The AR gene is located on the X chromosome and consists of eight exons; mutations or amplifications of this gene are often closely associated with the progression of prostate cancer and treatment resistance." (PMID 40008000, 2025). "Additionally, such co-exposures have been implicated in breast and prostate cancer pathogenesis, particularly through the modulation of estrogen and androgen receptor pathways." (PMID 41003403, 2025). "Additionally, TRAF4 overexpression has been implicated in prostate cancer, where it mediates K27-linked ubiquitination of the AR C-terminus, elevates intracellular cAMP levels, enhances E2F transcription factor activity, and promotes cell proliferation." (PMID 40990020, 2025). "Dysregulation or deletion of these genes, often observed in Y chromosome loss, has been linked to the aberrant activation of AR splice variants (e.g., AR-V7) and the NF-κB pathway, both of which contribute to the transition to castration-resistant prostate cancer." (PMID 40299503, 2025).
prostate carcinoma (continued). "In contrast, in prostate cancer cells harboring mutated AR, androgen stimulates TERT expression, indicating that androgen in conjunction with a mutated AR may promote telomerase activity within prostate cancer cells." (PMID 39871386, 2025). "AR gene mutations were also described in other diseases such as prostate cancer and Kennedy’s syndrome (spinal and bulbar muscle atrophy), and discoveries of such mutations also shed light on the importance of AR to reproductive biology, development, and tumorigenesis." (PMID 41163677, 2025). "For example, the higher androgen abundance observed in UGT2B17 KO individuals highlights the critical role of this pathway in regulating androgen bioavailability and androgen receptor signaling, especially in men, supported by its association with the progression of prostate cancer." (PMID 40264209, 2025). "It remains to be seen whether LSD1, CoREST1, or other CoREST complex proteins are involved in the transition of luminal prostate cancer cells toward NE states and loss of AR." (PMID 40479062, 2025). "AR-V7 is an androgen receptor splice variant that is hypothesized to be a potential molecular contributor to prostate cancer progression, given its role in conferring resistance to enzalutamide and abiraterone in preclinical studies." (PMID 40558274, 2025). "ScRNA-seq analysis of prostate cancer CTCs by David T. Miyamoto has shown that CTCs exhibit various alterations in androgen receptors (AR), including AR splice variants and point mutations, which are associated with clinical resistance to anti-androgen therapy." (PMID 38427120, 2024). "While data are limited due to its rarity, it is thought that amphicrine prostate cancer is often associated with metastatic disease and may be responsive to AR-targeted therapy." (PMID 38374116, 2024). "Overall, our study begins to dissect race-specific DNA methylation and AR-mediated transcriptional alterations that may underlie prostate cancer biology and are associated with clinical outcomes." (PMID 38566104, 2024). "The DELC study suggested that high baseline serum IL-6 levels at the time of enzalutamide administration may lead to a poor prognosis and that IL-6 in the serum may cause the progression of prostate cancer independently of AR." (PMID 38305451, 2024). "To assess the immediate impact of CBPD-409 on active transcription in prostate cancer cells, we next performed nascent RNA-seq (5-ethynyluridine sequencing) and discovered hallmark AR-regulated transcripts amongst the topmost significantly down-regulated genes." (PMID 38586029, 2024). "AR, which is activated by binding with circulating androgenic hormones is increasingly implicated with essential roles in various cancer types including prostate cancer pathogenesis and therapy and breast cancer." (PMID 39199690, 2024). "Hence, in the present study, the apoptotic mechanism of Astragalus membranaceus water extract (WAM) was elucidated in association with HSP27/AR signaling in prostate cancer cells." (PMID 38474045, 2024). "Furthermore, distinctive mutation patterns within the androgen receptor (AR) pathway, a vital driver of prostate cancer, have been observed in IDC‐P." (PMID 38379333, 2024). "HSD3B1 genotype was obtained in 287 patients with LV disease treated with ADT + AR antagonist only in the phase III Enzalutamide in First Line Androgen Deprivation Therapy for Metastatic Prostate Cancer (ENZAMET) trial and was associated with clinical outcomes." (PMID 39286977, 2024). "The authors concluded that AR c.2180G>T (R727L) could confer an up to sixfold increased risk of prostate cancer and account for cancer development in up to 2% of Finnish prostate cancer patients." (PMID 38773237, 2024). "Androgen receptor activity is in part responsible for maintaining prostate metabolism, and therefore any alterations to the receptor, including splice variants, can have significant implications to the metabolic profile of prostate cancer cells." (PMID 39858418, 2024).
prostate carcinoma (continued). "In contrast, another study focused on prostate cancer revealed a decrease in the mRNA levels of AR and AR-V7 (constitutively active variants), along with their targets kallikrein-related peptidase 3 (KLK3), FK506-binding protein 5 (FKBP5), and NKX3, following MLN4924 treatment and NAE knockdown." (PMID 39623094, 2024). "GATA2 and GATA3 are known AR co-regulators in prostate cancer but any race-specific association is unknown." (PMID 38566104, 2024). "One of the most investigated and therapeutically targeted oncogenes in prostate cancer is the androgen receptor (AR), which is frequently amplified and/or mutated in metastatic diseases whereby mediates the androgen-dependent transcription of growth-related genes toward prostate tumorigenesis." (PMID 38937754, 2024). "As a small molecule inhibitor of E2F8, MA may serve as a potential lead compound to overcome therapy resistance in prostate cancer caused by AR remodeling." (PMID 38605607, 2024). "This differed from our result that NCAPD3 inhibited miR-30a-5p expression, which was regulated by AR signaling, indicating antitumor miR-30a might function in both androgen-dependent and independent states associated with prostate cancer progression." (PMID 38561330, 2024). "However, given that differences in AR protein variant profiles in placenta and prostate cancer have been observed, it is likely that tissue-specific responses to androgens, and thus, changes in the direction of the regulation of AR-mediated transcripts occur." (PMID 38338965, 2024). "Additionally, a higher heterogeneity for AR gene mutations and splicing variants was identified in CTCs by sequencing, which is associated with the therapy resistance of patients with prostate cancers." (PMID 40026568, 2024). "Moreover, EIQPN robustly decreases the protein levels of AR and variants in prostate cancer cells by inducing AR protein degradation." (PMID 39359255, 2024). "Consistent with this, loss of BAG-1L abrogates AR signaling and reduces prostate cancer growth." (PMID 38412481, 2024). "These genetic differences may underlie the more aggressive prostate cancer phenotypes observed in this population, as elevated AR activity drives increased cell proliferation, survival, and resistance to apoptosis." (PMID 39600743, 2024). "Moreover, constitutive NFkB activation is associated with loss of androgen receptor expression and with an androgen-resistant phenotype of prostate cancer." (PMID 38675711, 2024). "Similarly, mTORC1 interacts with AR in prostate cancer cells and androgens reprogram mTOR–chromatin associations in an AR-dependent manner." (PMID 38727317, 2024). "In addition, WWL0245 demonstrated notable inhibitory impacts on the proliferation of AR-positive prostate cancer cell lines that are susceptible to BET inhibitors." (PMID 38389844, 2024). "Vesicular-associated AR-mCherry was also observed within 22Rv1 prostate cancer cells." (PMID 39858418, 2024). "However, mutations in androgen receptor gene proceed to androgen-independent prostate cancer growth." (PMID 39781138, 2024). "The role of the androgen receptor signaling pathway in prostate cancer has been widely proven, and the main mechanisms leading to tumor progression include mutations in the AR gene, synthesis of intra-tumoral androgens and abnormal AR proliferation and AR splicing." (PMID 39011396, 2024). "Targeting AR and associated pathways could be particularly beneficial in addressing the disparities observed in prostate cancer outcomes in the context of AA and EA men." (PMID 38566104, 2024). "Furthermore, a number of in vitro and in vivo prostate cancer models, including LNCaP cell lines expressing wild-type or mutated AR, have shown that radiation therapy upregulates AR signaling in CRPC, leading to radioresistance." (PMID 39769434, 2024).
prostate carcinoma (continued). "Furthermore, AR expression declines after cell passaging and the most commonly used prostate cancer cell line for AR studies, LNCaP, expresses a mutated form of the gene (T877A) that can modify its ligand-binding site and signalling." (PMID 37264224, 2023). "Stable PSA levels at radiographic progression may be associated with more aggressive, AR-independent variants of prostate cancer, and nearly a quarter of patients in the PREVAIL trial had stable PSA levels at the time of imaging progression." (PMID 36967752, 2023). "In addition to AR, AR-V (AR splice variants), and GR, prostate cancer progression and drug resistance involve a myriad of alternative mechanisms that have been extensively studied." (PMID 37860121, 2023). "MAOA is closely associated with the AR activity and development of prostate cancer." (PMID 37958805, 2023). "The dysfunction of AR is a major cause for the development of human prostate cancer." (PMID 37261210, 2023). "Similarly, CDK12 loss-of-function mutations in prostate cancer sensitizes the cancer cells to androgen receptor antagonists." (PMID 38132164, 2023). "Several studies have documented the association between AR splice variants and prostate cancer progression, including a group that published findings of AR splice variants binding to constitutively open chromatin to promote abiraterone resistance in prostate cancer." (PMID 37190127, 2023). "It showed strong efficacy in a patient-derived prostate cancer model expressing AR splice variants." (PMID 36768610, 2023). "Likewise, a naturally occurring (i.e., mutation-independent) splice variant that results in a truncated variant of the androgen receptor (AR-V7) is associated with castration-resistant prostate cancer." (PMID 36979496, 2023). "Furthermore, pinostilbene reduced the protein level of AR variant 7 in the Enz-resistant prostate cancer cell line 22Rv1 and inhibited cell viability and proliferation." (PMID 37794090, 2023). "This AR dependence remains a hallmark of prostate cancer (PC) cells." (PMID 37636316, 2023). "Mutations in the AR gene have been discovered in prostate cancer, and their incidence may increase with tumor progression." (PMID 37612283, 2023). "Furthermore, it has been demonstrated in several in vitro and in vivo prostate cancer models, including LNCaP expressing mutated or wild type AR, that radiation therapy can upregulate AR signaling in CRPC leading to radioresistance." (PMID 36768509, 2023). "Indeed, we previously reported that overexpression of alternative MED19 in androgen-dependent prostate cancer cells caused early-stage androgen-dependent prostate cancer cells to become androgen-independent by modifying AR-dependent gene expression." (PMID 37880276, 2023). "However, modifications in AR signaling, such as AR amplification, mutations such as mTOR signaling, or ligand-independent activation, can take place in prostate cancer." (PMID 37629142, 2023). "The aim of this study was to investigate whether mutations in GSTM1, T1, and the androgen-receptor gene and the androgen-receptor filamin protein A complex are associated with prostate cancer patients." (PMID 36824501, 2023). "The AR gene encodes the androgen receptor protein, which is a steroid-hormone-activated master regulator in prostate tissues and plays a critical role in prostate cancer progression." (PMID 37686146, 2023). "However, a prior study has found multiple splicing variant ARs (AR-Vs) in prostate cancer cells, xenografts, and tumors." (PMID 37047218, 2023). "Although the application of next-generation androgen receptor inhibitors such as enzalutamide and abiraterone has successfully improved the survival of patients with advanced prostate cancer, these treatments have also been associated with an elevated incidence of NEPC2,3." (PMID 38016952, 2023). "These mutations are frequently observed in prostate cancer and may contribute to disease progression by enhancing direct AR-DNA interactions." (PMID 36674785, 2023).